KLF8 (KLF transcription factor 8)
Description:
Transcriptional repressor and activator. Binds to CACCC-boxes promoter elements. Also binds the GT-box of cyclin D1 promoter and mediates cell cycle progression at G(1) phase as a downstream target of focal adhesion kinase (FAK).
Synonyms: BKLF3; ZNF741; DXS741
Tractability: PROTAC: UniProt records ubiquitination sites on it.
Gene: Protein-coding gene on chromosome X (56,232,356 to 56,291,531, forward strand). Ensembl gene ENSG00000102349.
Subcellular location: Nucleus
Subcellular location (Human Protein Atlas): Nucleoplasm
Gene Ontology:
Molecular function: DNA-binding transcription repressor activity, RNA polymerase II-specific; RNA polymerase II cis-regulatory region sequence-specific DNA binding; DNA-binding transcription factor activity, RNA polymerase II-specific; sequence-specific double-stranded DNA binding
Biological process: negative regulation of transcription by RNA polymerase II; regulation of transcription by RNA polymerase II
Cellular component: nucleoplasm; chromatin; nucleus
Homologues: Orthologues: chimpanzee KLF8 (100% identical), macaque KLF8 (98% identical), rabbit KLF8 (92% identical), guinea pig KLF8 (84% identical), mouse Klf8 (83% identical), pig KLF8 (82% identical), tropical clawed frog klf8 (53% identical), zebrafish klf8 (49% identical), Drosophila melanogaster luna (24% identical). Paralogues in human: KLF12 (43% identical), KLF3 (34% identical), KLF5 (28% identical), KLF4 (27% identical), KLF2 (25% identical), KLF7 (25% identical), KLF11 (25% identical), KLF6 (24% identical), KLF1 (24% identical), KLF15 (23% identical), KLF10 (22% identical), KLF18 (22% identical), and 10 more.
Diseases named in the same sentence as KLF8 in open-access papers:
KLF8 is named in the same sentence as 47 diseases in open-access papers, as found by Europe PMC text mining. Sharing a sentence is not in itself a finding about the gene and the disease. The quoted sentences say what the papers report.
breast carcinoma (26 papers, 2012 to 2025). "KLF8 was found to be among the most upregulated genes caused by OGT overexpression in breast cancer cells, suggesting a potential regulation of KLF8 by OGT." (PMID 37152043, 2023). "High KLF8 expression is associated with poor prognosis of breast cancer patients and was found to play a role in the HBP." (PMID 36077352, 2022). "Over-expression of KLF8 has been associated with a number of different cancer types including: ovarian carcinoma, renal cell carcinoma, hepatocellular carcinoma, breast cancer, gliomas, and gastric cancer." (PMID 25853515, 2015). "Similarly, poor outcome of breast cancer also associates with high mRNA level of KLF8, suggesting a potential role of KLF8 in the breast tumor development." (PMID 37152043, 2023). "Because CSCs population in breast cancer cells were enriched by KLF8 overexpression, and reduced by KLF8 knockdown, we hypothesized that KLF8 may regulate expression of components of the pluripotency network that are associated with breast cancer stem cells." (PMID 37152043, 2023). "Krüppel-like factor 8 (KLF8) has been strongly implicated in breast cancer metastasis." (PMID 26993780, 2016). "It has been suggested that KLF8 also plays a role in the activation of MMP-9 in breast cancer, and this may be an important signaling mechanism underlying invasion and metastasis." (PMID 25705690, 2015). "We wanted to know whether the high expression of EGFR in the breast cancer cells or tissues is associated with the high level of KLF8." (PMID 26025929, 2015). "In breast cancer cells, KLF8 also induces expression of MMP9, an enzyme critical for breaking through the extracellular matrix during cancer cell invasion and migration." (PMID 37152043, 2023). "Triple-negative breast cancer cells were genetically modified to generate KLF8 overexpressing or KLF8 knock-down cells." (PMID 37152043, 2023). "Depletion of KLF8 was able to abolish the effect of OGT overexpression in regulating mammosphere formation in TNBC cells, confirming the role of KLF8 downstream of OGT in breast cancer cells." (PMID 37152043, 2023). "By upregulating expression of these stem cell factors, KLF8 promotes the acquisition of stem-like cell phenotype in breast cancer cells." (PMID 37152043, 2023). "KLF8 is a driver of EMT in breast cancer and its expression in breast cancer cells is critical to the maintenance of breast cancer stem-like cells, as well as the expression of stem cells factors." (PMID 37838167, 2023). "KLF8 induces breast cancer (BC) invasion through the epithelial-stromal interaction 1/valosin-containing protein/NF-κB signaling pathway, which results in the degradation of IκBα and subsequent activation of NF-κB in the nucleus." (PMID 36761967, 2023). "KLF8 promotes human breast cancer cell invasion and metastasis by transcriptional activation of MMP9." (PMID 35205261, 2022). "In contrast to KLF4, KLF8 induces invasion, proliferation, and metastasis in breast cancer, and in human breast cancers, KLF8 and EGFR are co-elevated." (PMID 32552913, 2020). "Reduced expression of KLF3 in breast cancer upregulates the KLF8 gene, which is actually downstream of FAK." (PMID 33490232, 2020). "In breast cancer cells, KLF8 also cooperated with FAK to enrich the active MMP14 on the cell surface to facilitate the metastasis of the cancer cells." (PMID 31624471, 2019). "In human breast cancer, KLF8 promotes the invasion and metastasis of cancer cells by promoting the expression of matrix metalloproteinase 9 (MMP9)." (PMID 31624471, 2019). "For instance, KLF8 favors breast cancer cell invasion and metastasis by promoting the expression of MMP9." (PMID 31624471, 2019). "Here we report a novel signaling from KLF8 to C-X-C cytokine receptor type 4 (CXCR4) in breast cancer." (PMID 26993780, 2016). "Xenograft studies have pointed to the role of KLF8 in promoting invasive growth and metastasis of breast cancer." (PMID 26993780, 2016).
breast carcinoma (continued). "Nevertheless, it will be important to determine the detailed signaling mechanisms that operate the critical feed-forward wheel of KLF8/CXCR4/FAK in breast cancer cells." (PMID 26993780, 2016). "Taken together, our results support a critical role of CXCR4 engagement by CXCL12 downstream of KLF8 for breast cancer metastasis." (PMID 26993780, 2016). "We have recently performed a tissue microarray analysis of KLF8 expression in breast cancer patient tumors and have shown a positive correlation of KLF8 expression with invasive potential of the tumors." (PMID 26025929, 2015). "KLF8 has been extensively investigated within the context of different cancers, including hepatocellular carcinoma and breast cancer, where its activity has been found to induce invasion and metastasis." (PMID 25705690, 2015). "Krüppel-like factor 8 (KLF8) is a dual transcriptional factor critical for breast cancer progression." (PMID 26025929, 2015). "Taken together, these findings demonstrate a novel KLF8 to miR141/EGFR signaling pathway potentially crucial for breast cancer malignancy." (PMID 26025929, 2015). "Increased MMP activity results in both matrix remodeling and release of chemokines, cytokines and growth factors trapped within the ECM, promoting EMT process-KLF8-to-MMP9 signaling that promotes human breast cancer invasion." (PMID 26674531, 2015). "This novel KLF8-miR141-EGFR signaling axis plays a potentially important role in breast cancer progression." (PMID 26025929, 2015). "This is especially true considering a paper by Wang that demonstrated KLF8’s ability to promote human breast cancer cell invasion and metastasis by transcriptional activation of MMP9." (PMID 25853515, 2015). "Although much progress has been made in its transcriptional and post-translational roles and regulation as well as its nuclear localization, the molecular and signaling mechanisms by which KLF8 promotes human breast cancer progression remain largely elusive." (PMID 26025929, 2015). "For example, KLF8 was shown to stimulate the invasion of breast cancer cells through the induction of the matrix metalloproteinase gene MMP-9." (PMID 26320172, 2015). "KLF8 inhibits the expression of genes containing a CACCC element and KLF8 is overexpressed in several types of tumor cells, including gliomas, ovarian, renal, hepatocellular, gastric and breast carcinoma cells." (PMID 24604387, 2014). "When KLF8 was knocked down from the MDA-MB-231 human breast cancer cells, the cells formed much less metastases." (PMID 25485290, 2014). "Importantly, KLF8 is required for OGT to promote cancer stem-like cells phenotype in breast cancer, and KLF8 and OGT form a feed-forward loop to further induce stem-like cells traits in cancer cells." (PMID 37838167, 2023). "To test whether KLF8 can regulate chemoresistance in breast cancer cells, we overexpressed KLF8 in MDA-MB-231 and SUM159 cells, followed by treatment with increasing doses of paclitaxel for 48h." (PMID 37152043, 2023). "To test whether KLF8 expression is sufficient to increase stemness in breast cancer cells, we stably overexpressed KLF8 in TNBC cells MDA-MB-231 and SUM159 using lentiviral vectors." (PMID 37152043, 2023). "Our results show a potential role of KLF8 in regulating CSCs in breast cancer cells." (PMID 37152043, 2023). "To confirm that OGT and KLF8 co-regulate each other to promote stem cell properties in breast cancer, we overexpressed KLF8 in TNBC cells and transduced the cells with either control or shRNA targeting OGT, followed by assessing mammosphere formation efficiency." (PMID 37152043, 2023). "Recently, we observed increased levels of KLF8 in CSCs-enriched mammospheres, and increased OGT/O-GlcNAcylation upregulated KLF8 level in breast cancer cells, both in vitro and in vivo, suggesting a potential role of KLF8 in regulating CSCs properties in breast cancer cells." (PMID 37152043, 2023).
breast carcinoma (continued). "KLF8 levels are associated with chemoresistance in triple negative breast cancer patients and overexpression in breast cancer cells increased paclitaxel resistance." (PMID 37152043, 2023). "High levels of KLF8 expression were associated with breast cancer patients not-responding to taxanes compared to patients that responded." (PMID 37152043, 2023). "SMAD2 could be activated by the TGF-β1 signaling pathway, which, in turn, promotes KLF8 accumulation, leading to cancer progression in breast cancer." (PMID 36014967, 2022). "Additionally, recent studies also exhibited that KLF8 contributed to chemoresistance in breast cancer, gastric cancer and glioma." (PMID 33817271, 2020). "Indeed, KLF8 promoted the growth of almost all types of cancer cells, including breast cancer, gastric cancer, hepatocellular carcinoma, ovarian cancer, and bladder cancer." (PMID 31624471, 2019). "Three of the regions were small, containing just one gene: chr17 - RAB11FIP4; chr20 - MACROD2, overexpression of this gene has been implicated in oestrogen-independent growth; and chrX - KLF8, oncogenic in ovarian but not breast cancer cell lines." (PMID 28095868, 2017). "Together with our previous reports demonstrating a critical implication of KLF8 in malignant progression of breast cancer, this study further underscores KLF8 as an important regulator of breast cancer pathogenesis and malignancy and a potential therapeutic target with less side effects." (PMID 26993780, 2016). "KLF8 is a dual transcription factor known to express at marginally detectable levels in most normal tissue types and aberrantly overexpress in a number of human cancer types including breast cancer." (PMID 26993780, 2016). "Furthermore, microarray data profiling of invasive human breast cancer tissues downloaded from GEO and TCGA database was applied to examine the co-expression of KLF8 and CXCR4." (PMID 26993780, 2016). "Whether FAK upregulates KLF8 in the breast cancer cells by the same mechanism remains to be determined." (PMID 26993780, 2016). "Altogether, these results strongly suggest that EGFR may be another KLF8 target important in tumor progression of breast cancer patients." (PMID 26025929, 2015). "We have recently showed that KLF8 promotes breast cancer lung metastasis." (PMID 26025929, 2015). "Here we report a novel KLF8-EGFR signaling axis in breast cancer." (PMID 26025929, 2015). "Krüppel-like factor 8 (KLF8) has only recently been identified to be involved in tumor cell proliferation and invasion of several different tumor entities like renal cell carcinoma, hepatocellular carcinoma and breast cancer." (PMID 22276196, 2012). "Similarly, KLF8 has inter alia been implicated in EMT and invasion and DNA repair in breast cancer." (PMID 40001235, 2025). "Therefore, we hypothesized that KLF8 may also promote resistance to chemotherapy in breast cancer cells." (PMID 37152043, 2023). "We examined whether KLF8 expression correlated with patients’ response to chemotherapy, we used ROC plotter to assess the potential correlation between KLF8 expression and patient response to taxane, a first-line treatment for treating breast cancer patients." (PMID 37152043, 2023). "After confirming the aberrant overexpression of KLF8 in a panel of human ovarian and breast cancer cell lines and patient tumor tissues, we tested if KLF8 could transform non-tumorigenic human ovarian surface epithelial cell line T80 and mammary epithelial cell line MCF10A." (PMID 25485290, 2014). "KLF8 regulated mRNA and protein levels of CSCs markers, including OCT4, SOX2, MYC and NANOG in breast cancer cells." (PMID 37152043, 2023). "KLF8 and OGT co-regulate each other to form a feed-forward loop to promote CSCs phenotype and mammosphere formation of breast cancer cells." (PMID 37152043, 2023).
breast carcinoma (continued). "Immunoblot analysis of MDA-MB-231 cells overexpressing KLF8 showed both OGT and O-GlcNAc was elevated suggesting a potential feedback loop between KLF8 and OGT in breast cancer cells." (PMID 37152043, 2023). "FAK cooperates with Krüppel-like factor 8 (KLF8) to turn on MMP-14 and MMP-2 and indirectly regulates breast cancer cell invasion." (PMID 35163650, 2022). "In breast cancer, KLF8 promotes cell invasion and metastasis by activating the expression of MMP9 in breast cancer cells." (PMID 31624471, 2019). "Taken together, these results point to a potentially important feed-forward signaling wheel consisting of KLF8, CXCR4 and FAK and CXCL12 is a critical driving force for the cycling of the wheel in breast cancer cells." (PMID 26993780, 2016). "To test if KLF8 and CXCR4 are co-overexpressed in patient tumors, we performed immunohistochemical (IHC) staining for CXCR4 in a human breast cancer tissue microarray in which KLF8 expression was determined previously." (PMID 26993780, 2016). "Our previous study showed that KLF8 expression is undetectable in breast epithelial cells like MCF-10A, while it is aberrantly overexpressed in invasive breast cancer cells such as MDA-MB-231." (PMID 26993780, 2016). "We identified a highly correlated co-overexpression between KLF8 and EGFR in invasive breast cancer cells and patient tumor samples." (PMID 26025929, 2015). "In summary, this work provides significant new insights into the mechanisms of breast cancer progression and opens a new gate in the study of KLF8, miR141 and EGFR in breast cancer as potential biomarkers or therapeutic targets." (PMID 26025929, 2015). "Since the role of KLF8 on breast cancer stem cells has not been examined, we tested the role of KLF8 in regulating stem cells properties in breast cancer cells." (PMID 37152043, 2023). "KLF8 has also been shown to regulate breast cancer proliferation thus it’s possible that KLF8 regulates proliferation of both non-cancer stem cells and cancer stem cells." (PMID 37152043, 2023). "As expected, overexpression of KLF8 increased OGT and O-GlcNAc levels in breast cancer cells." (PMID 37152043, 2023). "Additionally, KLF8 directly induces EGFR gene expression and activates the MEK/ERK pathway in breast cancer to promote invasion and proliferation." (PMID 32552913, 2020). "It is known that both KLF8 and CXCR4 are aberrantly overexpressed in breast cancer." (PMID 26993780, 2016). "Thus, the identification of KLF8 as a critical feed-forward inducer of CXCR4 expression and activation of FAK in breast cancer cells presents an excellent therapeutic target to correct aberrant signaling of both FAK and CXCR4 specifically in cancer cells." (PMID 26993780, 2016). "We do not know how FAK is activated by the feed-forward loop of KLF8/CXCR4 in response to CXCL12 stimulation in the breast cancer cells used in this study." (PMID 26993780, 2016). "Samples from breast cancer metastasis, meningioma and non-neoplastic brain showed ubiquitous expression of KLF8, irrespective of the assumed proliferation rate." (PMID 22276196, 2012). "Importantly, knockdown of OGT in KLF8 overexpression reduced mammosphere formation in MDA-MB-231 cells, suggesting both OGT and KLF8 are needed to promote mammosphere formation and stem cell properties of breast cancer cells." (PMID 37152043, 2023). "Interestingly, our study also showed a co-regulation between OGT and KLF8, as KLF8 regulates OGT RNA and protein levels and KLF8 requires OGT for mammosphere formation, suggesting a potential feed-forward loop of OGT and KLF8 to regulate CSCs in breast cancer." (PMID 37152043, 2023). "KLF8 and OGT may serve as promising targets to overcome challenges in treating breast cancer." (PMID 37152043, 2023). "Interestingly, KLF8 and OGT coregulate each other and may form a feed-forward loop in breast cancer cells." (PMID 37152043, 2023). "Breast cancers with KLF8 showed worse OS than breast cancers without KLF8 expression." (PMID 34771527, 2021).